GSK3B (glycogen synthase kinase 3 beta)
Diseases named in the same sentence as GSK3B in open-access papers (continued):
Sharing a sentence is not in itself a finding about the gene and the disease.
Cerebral ischemia (continued). "Based on these in vitro and in vivo investigations, we conclude that Nrf2 activation downstream of GSK-3β participates in the neuroprotective effect of APG against cerebral ischemia." (PMID 33263567, 2020). "GSK-3β acts in memory function and cerebral ischemia-induced neurogenesis depending on the site of phosphorylation." (PMID 32351385, 2020). "The maintenance of phospho-GSK-3β by resveratrol in cerebral ischemia mediates the inactivation of caspase-3 and suppression of apoptosis." (PMID 32257906, 2019). "Our results showed that resveratrol treatment in cerebral ischemia regulates Akt and its downstream target, GSK-3β." (PMID 32257906, 2019). "In brain ischemia/reperfusion injury, rhMG53 increased the phosphorylation of Akt and GSK3β and exhibited neuroprotective function." (PMID 31779687, 2019). "The timescale by which GSK-3β inhibitors exhibit therapeutic properties in brain ischemia must be further examined." (PMID 30079246, 2018). "Here, current research in AD and brain ischemia is highlighted with particular focus on potentially unique mechanisms by which these disorders modulate GSK-3β regulated Nrf2 activity." (PMID 30079246, 2018). "Treatment with a phosphatidylinositol 3-kinase (PI3-K) inhibitor decreased the cerebral ischemia-induced phosphorylation of Akt and that of GSK-3β at its Ser9." (PMID 27866373, 2017). "We demonstrated that phosphorylation of GSK-3β at its Ser9 and that of Akt was significantly enhanced on day 7 after the cerebral ischemia, as was the number of NeuroD-positive cells." (PMID 27866373, 2017). "Although it remains to be determined what factors activate this pathway, our results suggest that PI3K/Akt-dependent GSK-3β signaling and subsequent expression of NeuroD were involved in the neurogenesis elicited by cerebral ischemia." (PMID 27866373, 2017). "The aim of this study was to determine the relationship between pathophysiological alteration of the GSK-3β signaling pathway and the initial stages of cerebral ischemia-induced endogenous neurogenesis in rats." (PMID 27866373, 2017). "Although neurogenesis is coordinately regulated by several factors, our findings imply that an IGF-1- and/or BDNF-independent PI3-K/Akt/GSK-3β pathway was enhanced by cerebral ischemia." (PMID 27866373, 2017). "The purpose of the present study was to determine the relationship between pathophysiological alteration of the GSK-3β signaling pathway and cerebral ischemia-induced endogenous neurogenesis in rats." (PMID 27866373, 2017). "Changes in activity of GSK-3β depend on the region of the injury and the severity of brain ischemia models." (PMID 27866373, 2017). "The inactivation of GSK-3β via tyrosine-216 dephosphorylation mediates neuronal survival after cerebral ischemia." (PMID 27566245, 2016). "A temporal increase in phospho-Akt after cerebral ischemia has been reported, and GSK-3β dephosphorylation at tyrosine-216 is accelerated as a downstream target of Akt." (PMID 27566245, 2016). "Effects of TubA on FGF-21 signaling, including up-regulation of β-Klotho and activation of ERK and Akt/GSK-3β after brain ischemia were consistent with its effects on FGF-21 mRNA and protein expression." (PMID 26790818, 2016). "Conversely, GSK-3β is inactivated to promote cell survival in short 5-min global ischemia models (mild cerebral ischemia models)." (PMID 25187832, 2014). "For example, in animal models of brain ischemia, STX recapitulates the neuroprotective effects of E2 via engagement of the PI3K/Akt pathway, resulting in the phosphorylation and inactivation of GSK3β and other Akt targets associated with neurodegenerative responses." (PMID 41019780, 2025). "In addition, electroacupuncture preconditioning can prevent cerebral ischemia/reperfusion injury through cannabinoid CB1 receptor (CB1R)-mediated phosphorylation of glycogen synthase kinase-3β (GSK-3β)." (PMID 38721046, 2024).
Cerebral ischemia (continued). "Moreover, the GSK3β isoform which is a part of the AKT/GSK3β signaling cascade has been reported to be a significant therapeutic target for cerebral ischemia (Koh S.-H." (PMID 35911974, 2022). "We hypothesized that the AMPK/AKT/GSK-3β signaling pathway might play a similar role in protecting neurons and reducing injury in cerebral ischemia-reperfusion, and focused our research efforts on this aspect." (PMID 36325190, 2022). "However, previous studies in some animal models have shown the opposite results regarding the possibility of GSK-3β regulating Nrf2 and protecting against cerebral ischemia, while some existing studies have defects in their research methods." (PMID 36139821, 2022). "It is well known that the PI3K/Akt/GSK-3β signaling pathway could be an important therapeutic target for neuroprotection against cerebral ischemia injury." (PMID 35814200, 2022). "The inactivation of GSK3β promotes neuronal survival after cerebral ischemia." (PMID 33924188, 2021). "In a further study, we will test another hypothesis whether AGNHW pre-treatment significantly inhibits GSK-3β phosphorylation at Tyr 216 for cerebral ischemia, before performing the clinical study." (PMID 33935731, 2021). "Our results illustrated that OA significantly counteracted cerebral ischemia-mediated injury through antioxidant effects induced by the regulation of the GSK-3β/HO-1 signaling pathway, implicating OA as a promising neuroprotective drug for the therapy of ischemic stroke." (PMID 35056059, 2021). "Using an in vivo transient focal cerebral I/R model and in vitro OGD/LPS‐induced injury models, the current study demonstrated that GSK‐3β phosphorylation‐regulated Nrf2 activation was involved in the promoted anti‐inflammatory microglia/macrophages polarization produced by SPC after brain ischemia." (PMID 34370899, 2021). "Importantly, in addition to regulating physiological processes, GSK-3β is also involved in the cellular response to various damage insults, including the development of cerebral ischemia." (PMID 33263567, 2020). "Thus, our finding suggests that resveratrol attenuates neuronal cell death in MCAO-induced cerebral ischemia and Akt/GSK-3β signaling pathway contributes to the neuroprotective effect of resveratrol." (PMID 32257906, 2019). "In addition, we elucidated the changes of GSK-3β by resveratrol treatment in MCAO-induced cerebral ischemia." (PMID 32257906, 2019). "GSK-3β has also emerged as a target in the treatment of brain ischemia." (PMID 30079246, 2018). "Interestingly, we demonstrated significant decreases in the level of IGF-1 on day 7 after cerebral ischemia, when the phosphorylation state of GSK-3β was at its maximum." (PMID 27866373, 2017). "Next, the role of PI3K/Akt/GSK-3β signaling pathway in the integrity of BBB was further investigated using the following antagonists: PI3K inhibitor wortmannin and GSK-3β siRNA in the model of warfarin-associated HT after cerebral ischemia." (PMID 27566245, 2016). "Thus, GSK-3β is a negative regulatory factor for Nrf2 in cerebral ischemia-reperfusion and OGD/R in neurons." (PMID 26838164, 2016). "Overactivity of GSK3β contributes to ketamine-induced developmental neuroapoptosis and cerebral ischemia-reperfusion impairment; accordingly, inhibition of GSK3β might reverse such damage." (PMID 27057548, 2016). "Therefore, whether GSK-3β inhibition can enhance Nrf2 activity and play a protective role after cerebral ischemia requires further exploration and confirmation." (PMID 36139821, 2022). "The detailed mechanism of the protective effects of simple O-substituted isoflavones against cerebral ischemia reperfusion might be related to the PI3K/AKT/ERK/mTOR or GSK-3β pathway, eNOS/Keap1/Nrf-2/HO-1 pathway, TLRs/TIRAP/MyD88/NFκ-B pathway, and Bcl-2-regulated anti-apoptotic pathway." (PMID 36142301, 2022).
Cerebral ischemia (continued). "Furthermore, some studies demonstrated that pharmacological increase in the phosphorylation of Akt and GSK3β protected against brain injuries induced by transient focal and global cerebral ischemia, and its neuroprotective effect was counteracted by administration of a PI3K inhibitor." (PMID 33924188, 2021). "Tanshinol borneol ester (DBZ) promotes the transformation of microglia from the M1 to M2 phenotype by activating the Akt/GSK-3β/NRF2 pathway and releasing a series of anti-inflammatory and antioxidant factors to protect against cerebral ischemia." (PMID 37361996, 2023). "Another hormone, adiponectin, regulated cerebral ischemia-reperfusion by blocking the NLRP3 inflammasome through regulating AMPK and GSK-3β phosphorylation and Nrf2 translocation." (PMID 35418995, 2022). "It has been shown that the PI3K/AKT/GSK3β signaling pathway plays a pivotal role in alleviating early brain injury in stroke, including SAH and cerebral ischemia." (PMID 35800132, 2022). "Some studies revealed that the inhibition of GSK3β phosphorylation at Tyr 216 deactivated GSK-3β, resulting in a benefit for cerebral ischemia." (PMID 33935731, 2021). "In this study, we demonstrated negative regulation of the transcription factor Nrf2 by GSK-3β after oxidative stress induced by OGD/R in vitro and cerebral ischemia-reperfusion in vivo." (PMID 26838164, 2016). "The core intersecting targets between cerebral ischemia and TB-2 are EGFR, SRC, GSK3B, MAPK1, and KDR, which may serve as potential therapeutic targets." (PMID 39376614, 2024). "Another alkaloid, ephedrine, derived from plants of the Ephedra genus, was demonstrated to attenuate cerebral ischemia injury in the middle cerebral artery occlusion rat model and BV2 microglial cells via Akt/GSK3β/Nrf2 pathway regulation and NLRP3 suppression." (PMID 35418995, 2022). "GSK-3β may regulate the Nrf2/ARE pathway and decrease oxidative stress in cerebral ischemia–reperfusion." (PMID 35359227, 2022). "GSK-3β siRNA and GSK-3β inhibitor alleviated cerebral I/R injury in rats, demonstrating that inhibition of GSK-3β could alleviate cerebral ischemia/reperfusion injury." (PMID 34079796, 2021). "In addition, in rat models of cerebral ischemia, transferring the AM gene to neuron induced anti-apoptotic effects, shown by the overexpression of Bcl-2, p-AKT, and p-GSK-3β." (PMID 34712429, 2021). "Interestingly, however, this brain ischemia model did not exhibit increased active GSK-3β and decreased nuclear Nrf2 simply as a consequence of MCAO/R." (PMID 30079246, 2018). "Present knowledge does not indicate brain ischemia directly alters GSK-3β regulation of Nrf2." (PMID 30079246, 2018). "However, involvement of GSK-3β in cerebral ischemia-induced endogenous neurogenesis is not yet fully understood." (PMID 27866373, 2017). "However, the specific mechanisms through which GSK-3β regulates Nrf2 have not been clarified in cerebral ischemia-reperfusion." (PMID 26838164, 2016). "However, the relationship between GSK-3β and Nrf2 in brain ischemia and reperfusion injury is not clear." (PMID 26838164, 2016). "However, there have been no studies showing how GSK-3β regulates Nrf2 in brain ischemia and reperfusion injury." (PMID 26838164, 2016). "In addition, as the protein levels of insulin-like growth factor-1 (IGF-1) and brain-derived neurotrophic factor (BDNF) were decreased, they might not have been essential for activation of the PI3-K/Akt/GSK-3β pathway after severe cerebral ischemia." (PMID 27866373, 2017). "Finally, in cerebral ischemia, Smad1 may mainly function as a downstream effector of canonical BMP signaling, or alternatively, as a mediator of other stroke-induced signaling pathways, such as brain-derived neurotrophic factor (BDNF) or GSK3β signaling." (PMID 26317208, 2015). "However, the effects of GSK-3β on Nrf2 and the Nrf2/ARE signaling pathway in cerebral ischemia-reperfusion had not been studied previously." (PMID 26838164, 2016).
myocardial ischemia (48 papers, 2013 to 2025). A disorder of cardiac function caused by insufficient blood flow to the muscle tissue of the heart. "PON2 can prevent acute myocardial ischemia‐reperfusion injury by regulating mitochondrial function and oxidative stress through the PI3K/Akt/GSK‐3β RISK pathway." (PMID 36840500, 2023). "In a previous study researchers induced the experimental model of myocardial ischemia-reperfusion injury in diabetic rats, and investigated the effect of TR on the phosphorylation of GSK-3β protein and apoptosis." (PMID 37034291, 2023). "The inhibition of GSK3β activity, as a consequence of phosphorylation of the Ser9 residue, confers a cardioprotective response in a multitude of rodent models of myocardial ischemia and AMI." (PMID 36012628, 2022). "A large number of studies have confirmed that the GSK3β/β-catenin signaling pathway is involved in the regulation of myocardial ischemia and hypoxia injury." (PMID 35340224, 2022). "Additional effects of agomelatine include protection of myocardial ischemia reperfusion injury by enhancing GSK-3β phosphorylation and repair of the blood−brain barrier through inhibiting the infiltration of macrophages into brain tissue." (PMID 35610704, 2022). "Activation of the AMPK/AKT/GSK-3β signaling pathway has been found to protect the myocardial ischemia-reperfusion injury and enhance glucose homeostasis in the diabetic liver." (PMID 36325190, 2022). "Inhibition of GSK3β stimulated mTOR signaling and inhibited autophagy through a rapamycin-sensitive mechanism during myocardial ischemia and IR." (PMID 34819832, 2021). "A protective component of GSK-3β inhibition during myocardial ischemia and reperfusion is to increase the threshold for mPTP opening as well as prevent BAX from translocating to the mitochondrial membrane." (PMID 34572418, 2021). "A number of studies have confirmed that activation of the PI3K/Akt/GSK3β pathway plays an important protective role in preventing myocardial ischemia." (PMID 34646152, 2021). "In terms of oxidative stress, resveratrol can reduce myocardial oxidative stress by stimulating Sirtuin1 (SIRT1) or inhibiting GSK3β in diabetic cardiac ischemia-reperfusion injury models and increasing nuclear factor E2-related factor 2 (Nrf2) expression." (PMID 34093716, 2021). "To investigate the possibility of functional interaction between ERK and GSK-3β, we compared the effects of their antagonism (prior to myocardial ischemia insult) on each other’s phosphorylation." (PMID 27768739, 2016). "The activation of Akt leads to phosphorylation of the downstream effectors GSK-3β, which is considered as a key player in regulating mitochondrial signaling and cell apoptosis during myocardial ischemia." (PMID 27657024, 2016). "Additionally, other miRNAs, including miRNA-34a, miRNA-199a, and miRNA-26a, affect myocardial ischemia/reperfusion injury via the GSK3β pathway." (PMID 40771283, 2025). "Moreover, KP was previously reported to effectively inhibit GSK3β activation in the treatment of many diseases, such as myocardial ischemia/reperfusion injury and heart failure." (PMID 40143103, 2025). "Here, we speculated that WSB1 may play a protective role in myocardial ischemia and regulate β-catenin signaling by mediating GSK3β degradation." (PMID 38395742, 2024). "The roles of GSK3β in myocardial ischemia have been reported in previous papers." (PMID 38395742, 2024). "Moreover, PON2 protects against acute myocardial ischemia‐reperfusion injury by regulating mitochondrial function and oxidative stress through the PI3K/Akt/GSK‐3β RISK pathway." (PMID 36840500, 2023). "The last two decades have witnessed an emerging consensus that the inhibition of GSK3β kinase activity could be a putative pharmacological target in myocardial ischemia and post-MI." (PMID 36012628, 2022). "Furthermore, GSK-3β inhibition alleviated myocardial ischemia reperfusion and doxorubicin induced heart damage." (PMID 36164369, 2022).
myocardial ischemia (continued). "The PI3-kinase/Akt activation leading to GSK-3β inactivation has been proposed to play a critical role in myocardial ischemia and compounds that have effects on this pathway may afford cardioprotection." (PMID 27657024, 2016). "Thus, during oxidative stress by myocardial ischemia assault Cavs can modulate intracellular signalling for EGCg-medicated cardioprotection via Akt/GSK-3β pathway." (PMID 24251870, 2013). "Resveratrol has been linked to upregulated adiponectin levels to prevent myocardial ischemia injury in diabetic mice, whereas berberine studies in diabetic cardiomyopathic rats have showed attenuated hypertrophy via activated AMPK and reduced GSK3β (glycogen synthase kinase 3 beta)." (PMID 37894760, 2023). "Pretreatment with liver ischemic preconditioning renders the heart less susceptible to subsequent severe myocardial ischemia and reperfusion-induced ventricular arrhythmia, which may occur as a consequence of phosphorylation of critical myocardial kinases ERK1/2 and GSK-3β." (PMID 27768739, 2016). "In a study of myocardial ischemia-reperfusion injury, researchers found that Puerarin can reduce the expression of inflammatory cytokines IL-6, IL-1β, and TNF-α through AMPK/Akt/GSK-3β /Nrf2 signaling pathway to prevent myocardial ischemia-reperfusion injury." (PMID 35482440, 2022). "It has been demonstrated that Erythropoietin reduces myocardial ischemia-reperfusion injury, and the activation of PI3K/Akt signaling pathway and down-regulation of GSK-3β gene expression were required." (PMID 30237226, 2019). "Linking the AKT/GSK-3β pathway and HIF-1α in myocardial ischemia/reperfusion injury advances our understanding of the molecular mechanisms underlying the cardioprotection of asiatic acid." (PMID 27657024, 2016). "A previous study also documented that RVS could prevent myocardial ischemia-reperfusion injury by regulating the phosphorylation of PI3K/Akt and GSK-3β, which plays a role in mitigating oxidative stress and subsequent damage to the heart." (PMID 40737341, 2025). "Furthermore, RVS postconditioning may prevent myocardial ischemia-reperfusion injury by inducing phosphorylation of PI3K/Akt and GSK-3β, while simultaneously promoting a higher Ca2+ load required to prevent mPTP opening, thereby mitigating oxidative stress." (PMID 40737341, 2025). "Therefore, although the modulation of upstream signals of GSK3β in myocardial-ischemia has been investigated previously, myocardial ischemia models were different, and none of these studies inhibited LRP5 directly." (PMID 31220102, 2019).